IL27 (interleukin 27)
Diseases named in the same sentence as IL27 in open-access papers (continued):
Sharing a sentence is not in itself a finding about the gene and the disease.
leukemia (4 papers, 2016 to 2026). A malignant (clonal) hematologic disorder, involving hematopoietic stem cells and characterized by the presence of primitive or atypical myeloid or lymphoid cells in the bone marrow and the blood. "Although we did not directly investigate the upstream mechanisms regulating CXCL10 induction in this study, our findings of reduced IFN-γ, TNF-α, and IL-27 expression in leukemia-bearing CXCL10-deficient mice underscore the need for further mechanistic studies." (PMID 41129238, 2026). "Our data together with previous reports indicate that IL-27, like its distinct properties in immune responses, may either stimulate or inhibit cancer cell growth depending on the context of different subtypes of leukemia." (PMID 27119567, 2016). "Moreover, we report that leukemia-derived proinflammatory cytokines, TNF-α, IL-27, and IFN-γ, induced CXCL10 in the meningeal stroma." (PMID 41129238, 2026). "Therefore, transferring IL-27 pre-stimulated polyclonal iTregs reduces systemic TNFα secretion, the expansion of cytokine secreting donor CD4 and CD8 T cells, and inflammatory cell infiltration in the colon, while preserving the graft-versus-leukemia activity." (PMID 32117306, 2020). "In conclusion, we have demonstrated for the first time that IL-27 can regulate tumor cell growth by favoring proliferation of human AML and erythroleukemic cells, suggesting that IL-27 may represent a promising potential therapeutic target for certain subtypes of leukemia." (PMID 27119567, 2016).
osteosarcoma (4 papers, 2014 to 2025). A usually aggressive malignant bone-forming mesenchymal neoplasm, predominantly affecting adolescents and young adults. "We aimed to investigate the association of IL-27 polymorphisms and serum IL-27p28 with osteosarcoma risk in a Chinese population." (PMID 25170932, 2014). "Therefore, to clarify this association, we analyzed the IL-27 gene -964 A/G (rs153109), 2905 T/G (rs17855750), and 4730 T/C (rs181206) and their haplotypes in osteosarcoma and normal controls in a Chinese population." (PMID 25170932, 2014). "Therefore, to further validate the association between IL-27 polymorphism and osteosarcoma risk, a larger sample size of population-bases study with other ethnicities involved is mandatory." (PMID 25170932, 2014). "A better understanding of the association between IL-27 gene polymorphism and osteosarcoma risk may identify an important role of IL-27 in the carcinogenesis of osteosarcoma, which provides clues that help to guide the treatment of this tumor." (PMID 25170932, 2014). "Distinct low serum IL-27 levels were presented in osteosarcoma patients of clinical stages III–IV and with tumor metastasis, indicating that low serum IL-27 levels were related to the progression of osteosarcoma." (PMID 25170932, 2014). "We did not observe any association of IL-27 genotypes, alleles, and haplotypes with osteosarcoma risk." (PMID 25170932, 2014). "Next, we investigated the association of IL-27 with clinical features of osteosarcoma patients; the results showed that IL-27 was not related to the patients’ age, gender, tumor size, histological type, and location." (PMID 25170932, 2014). "Therefore, by determining the serum levels of IL-27 and IL-12, we could know whether the lower levels of IL-27 are related to clinical situations other than osteosarcoma." (PMID 25170932, 2014). "We found that, in line with the results of IL-27, serum IL-12 levels were lower in osteosarcoma patients compared with healthy controls, and these two cytokines were positively correlated, suggesting that low serum IL-27 levels may be a more general phenomenon in osteosarcoma patients." (PMID 25170932, 2014). "In summary, the present study suggests that low serum IL-27p28 levels may be associated with development and progression of osteosarcoma; however, IL-27 gene polymorphism and their haplotypes may not contribute susceptibility to the osteosarcoma risk." (PMID 25170932, 2014). "Our results suggest that the IL-27 gene polymorphisms may not be important contributors in the carcinogenesis of osteosarcoma." (PMID 25170932, 2014). "Osteosarcoma had 25 significant relationships, notably including IL-4/IL-1β (r2 = 0.58, p = 0.000048), IL-12 p40/IL-4 (r2 = 0.47, p = 0.0015), CXCL5/IL-27 (r2 = −0.48, p = 0.001), CXCL14/IL-15 (r2 = 0.66, p = 0.0000021)." (PMID 41008853, 2025). "No previous studies currently reported the role of IL-27 in the carcinogenesis of osteosarcoma." (PMID 25170932, 2014).
plasmacytoma (4 papers, 2014 to 2023). Plasmacytoma is a localized mass of neoplastic monoclonal plasma cells that represents approximately 5% of all plasma cell neoplasms. "Adeno-associated viruses were harnessed as gene delivery vehicles for conducting the IL-27-immunogene therapy of melanoma, colon cancer, breast cancer, and plasmacytoma." (PMID 36742134, 2023). "Similarly, we found that AAV-IL-27 could also infect mouse plasmacytoma J558 cells in vitro, which resulted in IL-27 protein production during in vitro culture." (PMID 32292786, 2020). "Thus the present paper's prediction of the efficacy of different protocols of treatment of plasmacytoma in bone or soft tissue with IL-27 will need to be re-examined when more data become available that will enable us to include the important compartments of the immune and vascular systems." (PMID 24633175, 2014).
pneumococcal pneumonia (4 papers, 2014 to 2020). A febrile disease caused by STREPTOCOCCUS PNEUMONIAE. "The coincident timing between the appearance of IL-27 and enhanced susceptibility to secondary S. pneumoniae infection suggested this regulatory cytokine may contribute to the sensitivity to secondary pneumococcal pneumonia." (PMID 24408967, 2014). "The findings that IL-27 sensitized mice to secondary pneumococcal pneumonia suggested this cytokine profoundly altered host anti-pneumococcal defence in the lung." (PMID 24408967, 2014). "Therefore, the ability of IL-27-mediated IL-17A suppression in γδ T cells to sensitize mice to secondary pneumococcal pneumonia was dependent upon STAT1." (PMID 24408967, 2014). "However, treatment of IL-27 did not change pneumococcal counts and survival rates in WT mice, suggesting that IL-27 was expressed at a functionally adequate level in WT mice during secondary pneumococcal pneumonia." (PMID 24408967, 2014).
pulmonary tuberculosis (4 papers, 2015 to 2024). A bacterial infection that affects the lungs and is caused by Mycobacterium tuberculosis. "Therefore, we evaluated the relationship between IL-27 and IL-35 gene polymorphism, expression levels, and pulmonary TB (PTB) susceptibility." (PMID 38690286, 2024). "Our study was conducted on blood PBMCs of active pulmonary TB patients, and the only transcripts that showed significant upregulation up to 3.5 folds were mRNA for IL-27, so our findings support using IL-27 as a diagnostic biomarker for the early stages of pulmonary TB." (PMID 37460564, 2023). "Our study identified unique gene signatures (IL-27, STAT1, IRF1, TLR4, IL-15, IL-2RA, IL-24, TGFβ, CD28, CD80, NFATC1, and PTGDR2) that discriminate active pulmonary TB from uninfected controls using unstimulated PBMCs." (PMID 37460564, 2023). "Our data shows that interleukin-27 and CXCL10 are significantly related in pulmonary tuberculosis, and has-let-7b-5p and has-miR-30a-3p are also related to interleukin-27 and CXCL10." (PMID 35785034, 2022).
septic peritonitis (4 papers, 2012 to 2023). Septic peritonitis is an inflammatory condition of the peritoneum that occurs secondary to microbial contamination. "IL-27 is a regulator T-cells, having both pro- and antiinflammatory effects, and is rapidly induced in a murine model of septic peritonitis." (PMID 23107287, 2012). "Even in acute adult septic peritonitis, reduced bacterial clearance in the absence of IL-27 signaling was associated with a neutrophilic recruitment and inflammatory burst." (PMID 36891292, 2023). "Furthermore, genetic ablation of EBI3 or neutralization of IL-27 via a soluble IL-27 receptor fusion protein is protective in a murine model of septic peritonitis." (PMID 23107287, 2012).
Sjögren's syndrome (4 papers, 2012 to 2024). "In conclusion, this study identifies a role of DC-derived IL-27 in suppressing the pathogenesis of Sjögren's syndrome." (PMID 31754394, 2019). "Here, we reported that MSCs ameliorated experimental Sjögren's syndrome via IFN-β dependent IL-27 in DCs." (PMID 31754394, 2019). "However, whether IL-27 participates in pathological progress of Sjögren syndrome (SS) through regulating CD4+IL-10+ T cells remains unknown." (PMID 32849596, 2020). "To determine the clinical significance of IL-27, we assessed the correlation between IL-27 and European League Against Rheumatism (EULAR) Sjögren's syndrome Disease Activity Index (ESSDAI) scores." (PMID 31754394, 2019). "Nevertheless, to date, no study using the rAAV system has reported a role for IL-27 in Sjögren's syndrome (SjS)." (PMID 22827855, 2012).
toxoplasmosis (4 papers, 2012 to 2025). A parasitic disease contracted by the ingestion or fetal transmission of toxoplasma gondii. "Given that effector T cells from Pilrb−/− mice have an increased propensity for secreting IL-10, we assessed the production of IL-27 in WT and Pilrb deficient mice after i.p infection as a potential mechanism for the enhanced resistance to toxoplasmosis." (PMID 22479310, 2012). "The use of murine models of toxoplasmosis has revealed many of the inhibitory activities of IL-27, and the datasets presented here highlight the ability of IL-27 to influence HSPCs to restrain monocyte/macrophage induction." (PMID 41396163, 2025). "The use of murine models of toxoplasmosis have revealed many of the inhibitory activities of IL-27, and the datasets presented here highlight the ability of IL-27 to influence HSPCs to restrain monocyte/macrophage induction." (PMID 39868131, 2025). "Previous studies have shown that during toxoplasmosis or trypanosomiasis the absence of IL-27 results in enhanced CD4+ T cell responses which contribute to increased accumulation of inflammatory monocytes." (PMID 39868131, 2025).
trypanosomiasis (4 papers, 2015 to 2025). Infection with protozoa of the genus trypanosoma. "Having demonstrating that IL-27 is crucial for dampening trypanosomiasis-associated CD4+ T cell activation, needed for prolonged survival, we next addressed the mechanism of CD4+ T cell-mediated mortality of infected IL-27R-/- mice." (PMID 26222157, 2015).
Chronic Lymphocytic Leukemia (3 papers, 2023 to 2025). "This study provides the first direct evidence that interleukin-27 (IL-27) modulates immune checkpoint pathways in chronic lymphocytic leukemia (CLL)." (PMID 41296385, 2025). "Based on these observations, it appears that IL-27 may exert different effects depending on the tumour type; thus, there is a need to thoroughly investigate its role in chronic lymphocytic leukemia (CLL)." (PMID 41296385, 2025). "The total CD19+ B cells from patients with chronic lymphocyte leukemia (CLL) stimulated with IL‐27 showed elevated apoptosis of B cells and downregulated proliferation of B cells, whereas IL-27 stimulation on CD19+ B cells from healthy controls did not promote B-cell apoptosis." (PMID 38566992, 2024).
Cirrhosis (3 papers, 2015 to 2025). A chronic disorder of the liver in which liver tissue becomes scarred and is partially replaced by regenerative nodules and fibrotic tissue resulting in loss of liver function. "Constrained IL-27 mediated IgA production could be favorable for CHB patients as recent study reported the association of high serum IgA level with cirrhosis and served IgA as an independent and potential biomarker for cirrhosis." (PMID 33584666, 2020). "Yet we observed presence or absence of cirrhosis in HCC patients not reflecting expression of IL-6, IL-27, TNF-α, and VEGF." (PMID 25908103, 2015).
cutaneous leishmaniasis (3 papers, 2012 to 2018). Leishmaniasis affecting the skin. "Moreover, skin lesions of patients affected by cutaneous leishmaniasis caused by L. (V.)braziliensis showed a stronger correlation between IL-10 expression and proinflammatory cytokines such as IFN-γ, IL-27, and IL-21, rather than with FoxP3+ cells." (PMID 29743809, 2018). "The addition of IL-27 to PBMC cultures from patients with CL and ML did not interfere with the production of IL-10 by these cells, confirming that IL-27 did not have an effect on regulating the strong inflammatory response observed in human cutaneous leishmaniasis in this study." (PMID 24485388, 2014).
diabetic retinopathy (3 papers, 2018 to 2024). "Clinical studies further reveal that IL-27 is associated with T2DM complications, such as diabetic retinopathy, where IL-27 concentrations in aqueous humor positively correlate with blood glucose, lipid levels, and HbA1c." (PMID 39906735, 2024). "Elevated IL27 levels have been previously measured in the aqueous humor of patients with diabetic retinopathy." (PMID 36536319, 2022).
dilated cardiomyopathy (3 papers, 2020 to 2025). Cardiomyopathy which is characterized by dilation and contractile dysfunction of the left and right ventricles. "Elevated IL-27 mRNA levels were observed in the heart tissue of human dilated cardiomyopathy patients, and an IL-27 gene polymorphism involving SNP rs153109, rather than SNP rs17855750, predisposes to dilated cardiomyopathy in the Chinese Han population." (PMID 32194399, 2020).
encephalomyelitis (3 papers, 2016 to 2022). Inflammation of the brain and the spinal cord. "The results suggested that IL-27 may not mediate the control of virus replication in EV71-infected patients, different from HIV-infected patients or JHMV-induced encephalomyelitis." (PMID 27403033, 2016).
enterocolitis (3 papers, 2022 to 2024). An inflammatory process affecting the small intestine and colon. "In murine enterocolitis, oral delivery of IL‐27‐secreting L. lactis (LL‐IL‐27) improved survival significantly." (PMID 39439496, 2024). "Consistent with previous literature, IL-27 treatment significantly decreased the expression of RORγt (retinoic-acid-receptor-related orphan nuclear receptor gamma) in the colons of enterocolitis mice, thereby decreasing the expression of both IL-17A and IL-17F." (PMID 35082553, 2022).
eosinophilia (3 papers, 2017 to 2020). "This sustained eosinophilia in the absence of CD4+ T cells may be explained by the ability of IL-27 to inhibit proliferation and cytokine production by type 2 innate lymphoid cells (ILC2s)." (PMID 28129374, 2017).
fibrosarcoma (3 papers, 2013 to 2016). A malignant mesenchymal fibroblastic neoplasm affecting the soft tissue and bone. "We therefore examined the effect of IL-27 signaling on MCA-induced fibrosarcoma development by administering MCA to groups of Il27ra+/+ or Il27ra−/− mice." (PMID 23554861, 2013). "Dependency on STAT1 was confirmed by the lack of expression in IL-27-treated U3A cells, a STAT1-deficient human fibrosarcoma line." (PMID 27780205, 2016).
gastritis (3 papers, 2020 to 2024). Inflammation of the stomach. "IL-27 expression levels are high following HP infection, in IL-27-deficient mice developed more severe gastritis, IL-27 seems to be protective in mice." (PMID 39193325, 2024). "In this model, researchers administered high-dose tamoxifen to induce parietal cell atrophy and spasmolytic polypeptide-expressing metaplasia (SPEM) and found that IL-27-deficient mice developed more severe gastritis, atrophy and SPEM compared to control mice." (PMID 39193325, 2024). "Mice deficient in IL-27 display more pronounced gastritis, atrophy, and spasmolytic polypeptide-expressing metaplasia (SPEM) than their wild-type counterparts." (PMID 37504250, 2023). "In conclusion, IL-27 is a cytokine with both pro- and anti-inflammatory properties and the data obtained so far suggest a possible role for IL-27 in the pathogenesis of HP+ gastritis, although its role in AIG remains to be fully elucidated." (PMID 39193325, 2024). "Moreover, the administration of recombinant IL-27 significantly reduced the severity of inflammation and SPEM in mice with gastritis." (PMID 39193325, 2024). "Moreover, other inflammatory cytokines and chemokines (IL-27, IFN-β, IL-1α, IL-23, IL-22P70, TNF-α, IL-17A, IL-10, IL-1β, and MCP-1) were not showed dose-dependent changed in DFMO-treated mice compared to gastritis mice group." (PMID 32231118, 2020).
Hypercholesterolemia (3 papers, 2020 to 2022). An increased concentration of cholesterol in the blood. "Of note, the higher level of IL-27 in patients with hypercholesterolemia is ascribed to cTfh cells function and increased immunoglobulin G in their circulation." (PMID 33465845, 2021). "Also, IL‐27 was elevated in patients with hypercholesterolemia and was sufficient to induce an increase in Tfh cells." (PMID 33230950, 2020). "Additionally, hypercholesterolemia promotes germinal centre formation and the generation of autoantibodies against ds‐DNA and nucleosome in a TLR4/ IL27‐dependent mechanism." (PMID 36098213, 2022).
immune thrombocytopenia (3 papers, 2015 to 2016). "In addition, IL-27 inhibits cytotoxic T lymphocyte- (CTL-) mediated platelet destruction in primary immune thrombocytopenia." (PMID 27403033, 2016). "It has also been reported that serum/plasma levels of IL-27 decreased in epithelial ovarian cancer, while increased in cutaneous T-cell lymphoma, primary immune thrombocytopenia (ITP), and gastroesophageal cancer." (PMID 26014498, 2015).
intracerebral hemorrhage (3 papers, 2017 to 2022). A cerebrovascular disorder characterized by bleeding into one or both cerebral hemispheres including the basal ganglia and the cerebral cortex. "Recent studies demonstrated that IL-27 reduced ischemia–reperfusion injury in the brain in a mouse model and decreased neurological deficits and brain pathology in a model of intracerebral hemorrhage." (PMID 36064575, 2022). "Here, we show that the immunoregulatory cytokine interleukin-27 is upregulated centrally and peripherally after intracerebral hemorrhage." (PMID 28928459, 2017). "Additionally, an IL-27-neutralizing antibody reduced endogenous IL-27 and enhanced neurological deficits after intracerebral hemorrhage." (PMID 36064575, 2022). "Finally, interleukin-27 or lactoferrin administration results in reduced edema, enhanced hematoma clearance, and improved neurological outcomes in an animal model of intracerebral hemorrhage." (PMID 28928459, 2017).
lung disease (3 papers, 2016 to 2022). "Although IL-27/WSX-1 has been found to participate in many acute inflammatory diseases such as bacterial and parasitic infections, but very little information was available concerning its involvement in chronic inflammatory disease, especially in smoking-related lung diseases." (PMID 27994590, 2016).
lupus nephritis (3 papers, 2020 to 2025). Glomerulonephritis in the context of systemic lupus erythematosus. "This study aimed to identify associations between serum IL-27 and IL-23 levels and disease activity in Polish patients with different manifestations of SLE: neuropsychiatric lupus (NPSLE), and lupus nephritis (LN)." (PMID 34682911, 2021). "Notably, IL-27-conditioned MSC2 demonstrated superior therapeutic efficacy compared to conventional MSCs in a murine lupus nephritis model." (PMID 40642057, 2025).